RB1 (RB transcriptional corepressor 1)
Diseases named in the same sentence as RB1 in open-access papers (continued):
Sharing a sentence is not in itself a finding about the gene and the disease.
cancer (continued). "In addition, we found five genes with CNA losses (DMD, ARID1A, RB1, RAD51B and PTEN) that overlapped pan-cancer CNA drivers." (PMID 26429873, 2015). "Second, although RB1 is reduced in those cancers without CtIP/RBBP8, it is likely that the cell cycle progression is affected." (PMID 24403251, 2013). "An emerging paradox affecting Rb1 in cancer connects the relatively low number of mutations affecting Rb1 gene in specific human tumors, compared with the widely functional inactivation of pRb in most, if not in all, human cancers." (PMID 24381932, 2013). "We found that the expression ratio of CCND1 to CDKN2A clearly classified RB1-positive and -negative cancer lines, the predictive accuracy of which was superior to that of individual CDKN2A or CCND1, respectively." (PMID 21447152, 2011). "In the present study, we compared expression profiling of RB1-positive and -negative cell lines among 30 cancer cell lines, and identified a gene signature that was differentially expressed between the two groups." (PMID 21447152, 2011). "We collected a panel of cancer cell lines to be used for the identification of a gene signature that discriminates between RB1-positive and -negative cell lines." (PMID 21447152, 2011). "Although targeting RB1 loss or E2F1 has long been considered a promising strategy for cancer therapy, currently, there are no agents that directly target RB1/E2F1 in the market due to their undruggable characteristics as well as their general roles in biological processes in the healthy body." (PMID 41492471, 2026). "While it was not possible to generate valid RBNSigs for 18 other cancer types that lacked frequent RB1 defects or have limited proteogenomic data, we asked whether there exist patients with RBness in these additional cancer types." (PMID 40138429, 2025). "However, the RBNSig-high group also identified additional 328 patients lacking RB1 genomic defects, hereafter termed an RBness group that represents a transcriptional phenocopy of genomically defective RB1 cancers." (PMID 40138429, 2025). "Therefore, for mesenchymal cells, we would expect that the reduction of the slow viscous rate constant after AG879 treatment that reduces RB1 and KISS1 expression may lead to increased cancer cell migration and metastasis." (PMID 41028875, 2025). "In summary, our findings suggest that dysregulation of the RB pathway in cancers lacking RB1 genomic defects provides a molecular rationale for how these cancers could be treated." (PMID 40138429, 2025). "For example, CDK4/6 inhibitors were initially envisioned to (a) protect bone marrow cells (not necessarily all types of normal cells) (b) from chemotherapy with S-phase-specific drugs such as 5-fluorouracil and carboplatin (c) in patients with Rb1-negative cancers (resistant to CDK4/6 inhibitors)." (PMID 36913303, 2023).
cancer (continued). "In addition, our results showed that multiple GBMs were strongly correlated with RB1 wild type, but we have not found similar reports for other cancers." (PMID 37744696, 2023). "Meanwhile, HPV-positive and -negative tonsil cancers may likely have different preferences for cancer-related pathways and detailed somatic mutations: HPV-positive tumors tend to have higher rates of RB1, HRAS, and FGFR3 mutations." (PMID 36979829, 2023). "Interestingly, the cells in the minor clone are all VIM positive with or without CK expression, likely to be circulating TME cells with clonal alterations while the presence of RB1 and BRCA2 losses in the minor clone indicated the probability of the generation of a new cancer clone." (PMID 35729213, 2022). "A pan-cancer survival rate analysis was also performed to assess the prognostic values of these genes, and the results showed that these overlapping genes might be signatures in various cancers, such as RNF8 in KIRC, RB1 in OV and E2F6 in LIHC." (PMID 31709182, 2019). "As both CDKN2C and RB1 interact with G1/S cell cycle checkpoint through CDK4/6, they are potentially targetable through CDK4/6 inhibition, for which it has been shown in other cancers that co-deletion of CDKN2C and CDKN2A with functional presence of RB1 increases sensitivity in cell lines." (PMID 28427158, 2017). "We further provide evidence that Rb1 and compound K can chemosensitize CSCs to clinical anticancer drugs cisplatin and paclitaxel, inducing a synergistic cytotoxicity via Wnt/β-catenin signaling and epithelial-to-mesenchymal transition (EMT) regulation, both attractive targets for cancer treatment." (PMID 27825116, 2017). "In addition, CCNE2, PIK3CB, ITGAV, RB1, and BIRC2 involved in cancer pathway were also affected." (PMID 28567416, 2017). "Among them RB1 or ATM have a relatively clear rational and were reported be associated with poor prognosis in other types of cancer, but genes such as FAT2 or SMARCA4 may represent novel resistance genes." (PMID 27285986, 2016). "The majority of known driver gene amplifications (e.g., EGFR, ERBB2, MET, and MYC) and homozygous deletions (e.g., CDKN2A, PTEN, and RB1) were captured, with 320 RACSs (38%) containing at least one known putative cancer driver gene, in addition to 531 RACSs (62%) without known driver genes." (PMID 27397505, 2016). "Indeed, the importance of RB1 functional status in therapeutic response has not yet been elucidated for many cancer types." (PMID 26160835, 2015). "Finally, ESA+/CD24−/low/CD44+ cancer stem cells from RB-negative TNBC lines were consistently more sensitive to gamma-irradiation than RB-positive lines, whereas the effect of chemotherapy on the cancer stem cell fraction varied irrespective of RB1 expression." (PMID 24265703, 2013). "However, to identify patients with RB1-negative cancers, it is imperative to develop predictive biomarkers to classify RB1-positive and -negative tumors." (PMID 21447152, 2011). "RB1-negative cancers are more sensitive to some DNA-damaging agents such as 5-Fluorouracil, doxorubicin, and ionizing radiation, although the detailed mechanism for the RB1-negative selective effect remains unresolved." (PMID 21447152, 2011).
cancer (continued). "Quantitative RT–PCR confirmed that the E2F3 transcript level was increased in cancer (2.22-fold, log 2 scale; P=1.26 × 10−7, Student's t-test) and that the average RB1/E2F3 ratio was reduced by −0.87-fold (log 2 scale) from normal mucosa to cancer (P=3.52 × 10−6, Student's t-test)." (PMID 19156145, 2009). "Notably, SCLC is an RB1‐inactivated cancer that is not listed as a candidate for CDK4/6 inhibitors." (PMID 39136283, 2024). "Interestingly, when MYCN is high, the simple downregulation of RB1 is ineffective on cell growth or on reduction of cancer aggressiveness as implied by the Kaplan Meier graphs in which it is shown that E2F3 and MYCN expressions are strong prognostic markers of clinical outcome independently of RB1." (PMID 36982482, 2023). "For cancers lacking RB1 mutations, although the canonical functions of RB might still be disrupted through abnormal CDK activity or association with viral oncoproteins, intact non-canonical functions of RB in DNA repair might foster resistance to conventional cancer therapies." (PMID 33668093, 2021). "While the isogenic RB1 MCF10ATP53−/− cells were ideal for establishing the causal relationship between RB1 loss and corresponding synthetic lethal genes, we acknowledged that these cells may not mirror those cancers that exhibit RBness where it occurs in the absence of genomic RB1 defects." (PMID 40138429, 2025). "As a result, the absence of RB1 disrupts the negative regulation of ESRRG by RB1, enabling cancer cells to survive under hypoxic stress." (PMID 38672640, 2024). "Through pan-cancer bioinformatics analysis, we found that YAP expression is strongly downregulated in RB1 mutant SCLC cell lines, but not non-small cell lung cancer cell lines (NSCLC)." (PMID 37739954, 2023). "In conclusion, we demonstrate RB1 or HK1 as critical regulators of the cellular bioenergetic profile and identify the altered tumor metabolism as a potential therapeutic target for cancers lacking functional Rb protein." (PMID 36291051, 2022). "In the Bonome dataset (GSE26712), Adalnet selected only two not-isolated genes (RB1 and BRCA2) involved in two different cancer pathways." (PMID 27378931, 2016). "Up-regulation of NF1, RB1 and SUFU shows a negative effect on cancer growth, consistent with our previous report." (PMID 21765906, 2011). "Moreover, in cancer-related nonhistone methylation, SMYD2 methylates the RB1, ALK, and β-catenin proteins to regulate the cell cycle and cell proliferation, implying that SMYD2 is a potential therapeutic target for cancer treatment." (PMID 37121971, 2023). "In addition, expression profiling analysis of PRELP−/− mouse retina indicated that PRELP itself has ability to regulate cancer-related pathways, cell adhesion, and EMT without RB1 abnormality." (PMID 36230849, 2022). "Also the “Kegg cancer pathway” is picked up by both bioinformatics tools: g-profiler identifies the same list of genes among the known AR-interacting proteins as “DAVID”, only that RB1 is not included in the g-profiler gene list." (PMID 22518120, 2012).
adenocarcinoma (73 papers, 2012 to 2026). A common cancer characterized by the presence of malignant glandular cells. "All transformed tumor and cell line samples exhibited loss of RB1, a phenomenon rarely observed in tumors that remained adenocarcinoma." (PMID 41516316, 2025). "In adenocarcinoma or p16INK4-negative tumors, the positive RB1 expression was also associated with the unfavorable outcomes (RR = 2.833, 95% CI: 1.532–5.239; P < 0.001; and RR = 3.273, 95% CI: 1.632–6.562, P < 0.001, resp)." (PMID 22619677, 2012).
adenocarcinoma (continued). "RB1 mutations have been reported in approximately 65% of SCLC cases and 4% of NSCLC (adenocarcinoma) cases." (PMID 35815661, 2022). "We identified frequent CNVs of the ATRX and RB1 genes in NENs and key driver mutations of the ARID1A, PIK3CA, CTNNB1, and MYC genes in nNENs, especially adenocarcinomas." (PMID 34422662, 2021). "Thus, loss of Pten in prostate epithelial cells leads to slow-growing and homogeneously AR+ adenocarcinoma whereas co-deletion of Pten and Rb1 drives formation of much more aggressive PCa that is heterogeneous in AR expression with many AR–/lo PCa cells." (PMID 39363904, 2024). "The RB1 alteration in this patient was found on repeat biopsy at the time of progression on first generation EGFR tyrosine kinase inhibitor (TKI), along with an acquired EGFR T790M mutation and a histopathology of adenocarcinoma." (PMID 30773851, 2019). "Of note, though CTCs from patients with neuroendocrine prostate cancer are more frequently nonclassical than those with patients with adenocarcinoma, the RB1 mutation was identified in classical EpCAM+ CTCs." (PMID 28228136, 2017). "In addition, in those p16INK4-negative or adenocarcinoma tumors, the RB1 status stratifies them into favorable and unfavorable groups." (PMID 22619677, 2012). "The retained RB1 expression in these mCRPC cases, along with its loss in NEPC, suggests a driver role of RB1 protein loss in NEPC, further highlighted by the frequently observed concurrent loss of RB1 expression in the adenocarcinoma component in mixed PCA-NEPC." (PMID 38398199, 2024).